BRCA1 (BRCA1 DNA repair associated)
Diseases named in the same sentence as BRCA1 in open-access papers (continued):
Sharing a sentence is not in itself a finding about the gene and the disease.
breast cancer (continued). "The aim of this study was to analyze the results of platinum-based chemotherapy for BRCA1-positive breast cancer in a neoadjuvant setting." (PMID 29719582, 2018). "In this study, we show that tamoxifen-resistant breast cancer cells are resistant to DNA-damaging chemotherapy because of upregulated BARD1 and BRCA1, which is caused by activated PI3K/AKT pathway." (PMID 29686231, 2018). "XIST has also been shown to interact with BRCA1, a gene frequently mutated in triple negative breast cancers (TNBC) further implicating its role in breast cancer." (PMID 29732012, 2018). "To demonstrate a direct functional link between PIN1 expression and LYN activity, we knocked down PIN1 in primary mouse Brca1 null cells and cells from a BRCA1 mutant human breast cancer cell line and the BRCA1 mutant PDX." (PMID 30590041, 2018). "In Egypt, 60 breast cancer patients, derived from 60 families, were selected for molecular genetic testing of BRCA1 and BRCA2 genes." (PMID 29409476, 2018). "Breast cancer genes 1 and 2, BRCA1/2 have been very well studied since their discovery in 1994 and 1995." (PMID 29339979, 2018). "In the 2001- study, 82 patients who contracted breast cancer prospectively after being recommended breast cancer screening based on their family history, were BRCA1/2 tested." (PMID 29339979, 2018). "The breast cancer susceptibility genes BRCA1 and BRCA2 (BRCA1/2), well-known members of the FA/HR-pathway, have a well-described role in hereditary breast and ovarian cancer." (PMID 29719599, 2018). "The dysfunctional BRCA1 pathway is involved in the pathogenesis of both hereditary and sporadic breast cancers." (PMID 28646826, 2018). "Additional analyses of cDNA microarray data from van’t Veer showed that BRCA1-related tumours have a sporadic basal-like breast cancer gene expression profile." (PMID 29928469, 2018). "We then selected a BRCA1 mutant, ER-negative human breast cancer cell line, SUM149, in which p16 is deleted and VIM is expressed in 10–30% of total cells." (PMID 29996906, 2018). "In a murine genetically engineered model of BRCA1 breast cancer, the combination of anti-CTLA-4 and anti-PD-1 therapy with cisplatin-based chemotherapy resulted in improved survival." (PMID 30120226, 2018). "BRCA1, which is involved in homologous recombination DNA repair, is alternatively spliced in breast cancer to exclude exon 11 that contains the nuclear localisation signal." (PMID 29848666, 2018). "Despite these specificities, the majority of breast cancer genetics studies performed in North Africa remain restricted to the investigation of the BRCA1 and BRCA2 genes." (PMID 29879995, 2018). "The basal-like breast cancer cell line, HCC1937, harbours a nonsense mutation in the BRCA1 gene leading to a premature stop codon prior to the DNA binding domain." (PMID 30323900, 2018). "The BRCA1 c.5470_5477delATTGGGCA and BRCA2 c.7878G>A were the most prevalent mutations among Chinese breast cancer patients that reside in US and other countries." (PMID 29487695, 2018). "Presence of β‐hCG either due to endogenous expression or by exogenous supplementation promotes tumorigenesis by inducing migration, invasion and stemness predominantly in BRCA1 mutant breast cancer cells." (PMID 29460395, 2018). "Pathogenic mutations in BRCA1 and BRCA2 genes explain ~ 30% of the cases of families with a high risk of cancer and ~ 15% of breast cancer familial relative risk." (PMID 29678143, 2018). "The results of the study confirm the high pCR rate in BRCA1-positive breast cancer after platinum-based neoadjuvant chemotherapy." (PMID 29719582, 2018). "One of the most frequently discussed mutations in breast cancer literature is the germline mutation in BRCA1 and BRCA2 genes, which accounts for about 25% of inherited breast cancers and 10% of all breast cancers." (PMID 29713580, 2018).
breast cancer (continued). "In breast cancer inactivation of BRCA1 and/or 2 by promoter methylation is currently considered for treatment with the same PARP inhibitor in a trial (clinicaltrial.gov, NCT03205761)." (PMID 29368212, 2018). "High circulating levels of IGF-I increase the risk of breast cancer in women from families with BRCA 1/2 mutations and BRCA1 deficiency has been linked to an increase in IGF-I in both in vitro and in vivo models." (PMID 30323899, 2018). "In general, Hong Kong has the highest estimated risk of breast cancer by age 70 years for both BRCA1 and BRCA2 carriers, but still much lower than that in Caucasians (40-87% for BRCA1 and 27-84% for BRCA2)." (PMID 29861850, 2018). "Previously published case reports have shown that carriers of BRCA1 and BRCA2 mutations formed angiosarcomas following radiation treatment of breast cancer." (PMID 29515789, 2018). "This combined analysis demonstrated that seven of the nine miRNA genes had BRCA1 ChIP-seq binding suggesting a potential mechanism whereby BRCA1 regulates the expression of these miRNAs in breast cancer." (PMID 30323900, 2018). "The information reviewed in the Clinical Variation database showed that the BRCA1 and BRCA2 pathogenic variants found in our study have been reported in patients with breast cancer or ovarian cancer patients." (PMID 29997359, 2018). "We further demonstrate that treatment of Brca1-mutant mammary tumors with vinblastine, which induces cyclin B1, significantly reduced tumor progression." (PMID 30327455, 2018). "The most common breast cancer predisposing syndrome is hereditary breast and ovarian cancer syndrome (HBOC) that is related to pathogenic germline variants in BRCA1 (OMIM 113705) and BRCA2 (OMIM 600185) genes." (PMID 29868112, 2018). "Together, BRCA1 and BRCA2 mutations account for about 20–25% of hereditary breast cancers and about 5–10% of all breast cancers." (PMID 29445722, 2018). "Of 189 BRCA1/2MUT+ carriers with unilateral breast cancer, 8 were found to have contralateral breast cancer." (PMID 30203341, 2018). "While 90–95% of breast cancer cases occur sporadically, approximately 5–10% are hereditary, with breast cancer gene 1 and 2 (BRCA1 or BRCA2 hereafter) being the most common." (PMID 30001421, 2018). "Among the 3 germ line mutation, 2 were similar to that observed in the NTM patients with breast cancer history (chromosome position: 41245471, BRCA1; 32906729, BRCA2)." (PMID 30054559, 2018). "F112 discusses more specific genetic risks of breast cancer (BRCA1 or BRCA2 positive), while F47 (similarity 92%) chats about more general risks." (PMID 30497991, 2018). "When we examined the age at diagnosis of breast cancer by gene, we found that the patients with pathogenic variants in PTEN, BRCA1, and BRCA2 were significantly younger at diagnosis compared to patients without pathogenic variants." (PMID 30287823, 2018). "The absolute risk of breast cancer by the age of 80 years is 75% and 76% for protein truncating mutations of BRCA1 and BRCA2, respectively, far higher than any other mutation associated with hereditary breast cancer." (PMID 30174725, 2018). "Here, we report the results from the combined analysis of BRCA1-dependent expression profiles and BRCA1 ChIP-seq data, which were verified in breast cancer cell lines." (PMID 29757984, 2018). "Examination of the role of BRCA1 and BRCA2 in the DNA damage response has led to the identification of several breast cancer susceptibility genes such as FALB2, CHEK2, BRIP1, all of which interact directly or indirectly with BRCA1 or BRCA2." (PMID 30249004, 2018).
breast cancer (continued). "In clinics, different trials on breast cancer patients with BRCA1/2-defective tumors demonstrated that PARP inhibitors, such as olaparib, enhance the therapeutic response when administrated as single agents or in combination with platinum compounds." (PMID 30234015, 2018). "Germline pathogenic variants in BRCA1, BRCA2 and PALB2 DNA repair genes are associated with high risk of developing breast cancer." (PMID 30410870, 2018). "BRCA1/2 are tumor suppressor genes (TSG) and the germline mutations of either results in an increased risk of ovarian cancer and early onset breast cancer associated with hereditary breast and ovarian cancer (HBOC) syndrome." (PMID 29690565, 2018). "To this end, we analyzed the expression level of the BRCA1 gene by real-time RT-PCR in the newborn carriers, woman carriers, and BRCA1 methylation-positive breast cancer patients." (PMID 30049288, 2018). "There are only a few randomized data that compared platinum agents to standard of care in metastatic breast cancer patients for whom BRCA1/2 germline status is known." (PMID 30544963, 2018). "BRCA1 and BRCA2 are major breast cancer susceptibility genes whose pathogenic variants are associated with a significant increase in the risk of breast and ovarian cancers." (PMID 30453575, 2018). "p18−/− mice in the Balb/c background developed ER-positive luminal-type mammary tumors whereas p18−/−;Brca1+/− double mutant mice formed ER-negative basal-like mammary tumors." (PMID 29996906, 2018). "This property has been suggested to have important implications for acquisition of chemoresistance; the breast cancer tumor suppressor BRCA1 promotes HDR by mediating DNA end resection and RAD51 loading." (PMID 29475976, 2018). "On the other hand, medullary phenotype without family anamnesis did not have any class 4 or 5 somatic mutations in the BRCA2 gene, pointing out to the role of the BRCA1 gene only in breast cancer with medullary features." (PMID 29453630, 2018). "In a retrospective monocentric Dutch series, 35 BRCA1- and 13 BRCA2-associated advanced breast cancers receiving either paclitaxel or docetaxel were compared with 95 sporadic forms." (PMID 30544963, 2018). "More recently, studies have also identified BRCA1/2 status as clinically relevant in the selection of therapy for patients already diagnosed with breast cancer." (PMID 29867226, 2018). "In breast cancer cell lines, BRCA1 is shown to positively regulate FOXA1 and FOXO3 expression by interfering with EZH2-mediated promoter methylation." (PMID 30558184, 2018). "For women with a BRCA1/2 mutation the association between exposure to ovarian stimulation for IVF and breast cancer risk has hardly been studied." (PMID 29937543, 2018). "Despite these exciting developments, chemotherapy is still the first-line therapy for BRCA1-related breast cancers." (PMID 30558184, 2018). "The model presented here suggests an opportunity to target the lipogenic pathway in BRCA1-related breast cancers." (PMID 30323899, 2018). "BRCA1 and BRCA2 mutations confer a substantial breast risk of developing breast cancer to those who carry them." (PMID 30103738, 2018). "A careful analysis of western blot images unveils that the expression of HIF-1α is significantly increased in the hereditary breast cancer cells, suggesting a specific role of BRCA1 in regulating this factor." (PMID 29584711, 2018). "RANK+ luminal progenitors in BRCA1 mutation carriers are highly proliferative, and inhibition of its ligand RANKL attenuates mammary tumor formation in Brca1 knockout mice." (PMID 30558184, 2018). "The onset age of breast cancer in the BRCA1-positive group was significantly lower than that of the BRCA-negative group (P < 0.001)." (PMID 29176636, 2018).
breast cancer (continued). "To demonstrate the relevance of cytoplasmic BRCA1 in cell metabolism, we confirmed the association between endogenous BRCA1 and phosphorylated ACCA in MCF7 and T47D breast cancer cells using co-immunoprecipitation." (PMID 30323899, 2018). "For example, miR-182, miR-181a/b, miR-28, and miR-146 have been demonstrated to target BRCA1 in breast cancer cells." (PMID 30234015, 2018). "Of particular interest for SNPs associated with DTF were SNPs in close proximity to the soybean Glyma. g275100, an orthologue to the human breast cancer gene BRCA1." (PMID 29490606, 2018). "Breast cancer type 1 (BRCA1) was identified more than 20 years ago, and is normally expressed in the breast and other tissues with multiple functions." (PMID 29757984, 2018). "Reported findings of breast cancer have suggested prognosis and predictive biomarkers based on alterations in genes (e.g. BRCA1 and BRCA2) and protein expression (e.g. mTOR, ras, PKC)." (PMID 29438405, 2018). "In this study, one BRCA1 large deletion (r.5194_5406 del) was identified from local breast cancer patient by this method with a frequency of 2.08% (1/48) among all mutations." (PMID 29487695, 2018). "A study also revealed that ID4 and BRCA1 expression are inversely related and unmethylation of ID4 is associated with BRCAness of breast cancer cells." (PMID 29298879, 2018). "Breast cancer studies by Pawitan and Bild demonstrated that CXCL1 expression had a significant increase in the BRCA1 mutant (P = 0.0035) and triple-negative (P = 0.0005) breast cancer patients, respectively." (PMID 30158589, 2018). "We selected 45 candidate genes based on gene expression correlation data, obtained from two GEO (Gene Expression Omnibus) datasets and TCGA data of human breast cancer, compared to BRCA1 expression levels." (PMID 29757984, 2018). "Identifying female carriers of BRCA1 and BRCA2 mutations is imperative for prevention of ovarian cancer and breast cancer." (PMID 29506471, 2018). "Using 2D-DIGE we analyzed and compared the mitochondrial proteomic profile of sporadic breast cancer cell line (MCF7) and BRCA1 mutated breast cancer cell line." (PMID 29584711, 2018). "The mutations of BRCA1 and BRCA2 in human medicine are hereditary and an indicator of a high possibility of high-grade breast cancer development." (PMID 30373614, 2018). "Hereditary factors such as germline deleterious mutations in BRCA1 and BRCA2 genes significantly increases predisposition to breast cancer." (PMID 29713003, 2018). "All widely used BRCA1 mutant breast cancer cell lines have deletions in either RB or p16, reflecting the importance of inactivation of the INK4-CDK4/6-RB pathway in the proliferation of BRCA1-deficient tumor cells." (PMID 29996906, 2018). "Defects in BRCA1 and BRCA2 genes have been recognized as risk factors for human breast cancer and ovarian cancer." (PMID 29651417, 2018). "The frequencies of BRCA mutations were 10.5% from a cohort of 409 Chinese breast cancer patients in Northern China, and BRCA2 mutations were more common than BRCA1." (PMID 29487695, 2018). "BRCA1 and BRCA2, which were initially named as breast cancer susceptibility genes 1 and 2, are heavily associated with breast and ovarian cancers." (PMID 30551670, 2018). "Data from a retrospective study indicate that BRCA1/2 carriers advanced breast cancer patients receiving CMF-like regimen have similar outcomes than wild-type subjects." (PMID 30544963, 2018).
breast cancer (continued). "Examples of predictive methylated genes are MGMT in glioma (temozolomide), BRCA1 in breast cancer (PARP1 inhibitors, cisplatin, and chemotherapy), and PRKCDBP in colon cancer (oxaliplatin), among others." (PMID 29445424, 2018). "Breast cancer patients with a deficit for BRCA1 are known to display an increased sensitivity to PARP inhibitors or DNA-damaging agents such as platinum compounds." (PMID 29867779, 2018). "This cell line shares many genetic (p16/p18 and Brca1 loss-of-function mutation) and phenotypical (ER negative with a subset of cells exhibiting EMT features) similarities with p16;Brca1 and p18;Brca1 mutant murine mammary tumor cells." (PMID 29996906, 2018). "To understand how BRCA1 exerts its tumor-suppressive effects by regulating FADD in breast cancer cells, we next checked the effect of BRCA1 overexpression on FADD-related signaling." (PMID 29757984, 2018). "The rationale for this strategy is the observed preclinical synergistic activity of this combination in murine models of breast cancer (either BRCA1-related or sporadic triple-negative)." (PMID 30347758, 2018). "Both BRCA1 and BARD1 are known to be tumor suppressor genes, whose mutations are associated with an increased risk of breast cancer." (PMID 29686231, 2018). "We have previously demonstrated that Brca1 mutation-associated breast cancers originate from luminal ER− progenitors and that c-KIT and LYN are expressed in mouse Brca1 mammary tumors." (PMID 30590041, 2018). "BRCA1 mutant breast cancers are typically TNBC and though TNBC incidences are higher in AA women compared to other ethnic groups, incidence of germline BRCA1 mutation is higher in European women." (PMID 30558195, 2018). "While displaying similar roles in HR, BRCA1- and BRCA2-associated breast cancer have very different pathology and biology." (PMID 30544963, 2018). "Women with BRCA1 and BRCA2 mutations who receive bilateral total salpingo-oophorectomy at or before the age of 40 benefit from a 40% reduction in the risk of breast cancer." (PMID 29713580, 2018). "In this study, we found that BARD1 and BRCA1 were highly expressed in tamoxifen-resistant breast cancer cells, which led to enhanced DNA damage repair and resistance to DNA-damaging chemotherapy." (PMID 29686231, 2018). "We have characterized the BRCA1 and BRCA2 variants in 307 unselected breast cancer patients in Puerto Rico." (PMID 30400234, 2018). "Women carriers of BRCA1 or BRCA2 mutation seem to have a potential risk of 72% and 69% to develop breast cancer and a risk of 44% and 17% to develop ovarian cancer respectively." (PMID 30340058, 2018). "Screening to identify BRCA1 and BRCA2 carriers is especially important because there are several preventative options which can lower the risk of developing breast cancer." (PMID 29713580, 2018). "Germ-line mutations in BRCA1 and BRCA2 genes are associated with ~60–90% probability of developing breast cancer and 40–60% life-time risk of ovarian carcinoma." (PMID 30211169, 2018). "For example, wild-type BRCA1 binds to the promoter of miR-155 in breast cancer cells, where it recruits histone deacetylase 2 (HDAC2) to promote chromatin condensation and gene repression." (PMID 30323900, 2018). "Two studies from China18 and Malaysia19 sequenced BRCA1/2 in >2000 selected and unselected breast cancer patients, respectively." (PMID 30287823, 2018). "Extensive work has focussed on the role of BRCA1 in the normal breast and in the development of breast cancer, the cell of origin for BRCA1 tumours and the protein-coding genes altered in BRCA1 deficient cells." (PMID 30323900, 2018). "ID4 (inhibitor of differentiation) protein is highly expressed in TNBC cells and down-regulates BRCA1 pathways and exhibits anchorage-independent growth of breast cancer cells." (PMID 29298879, 2018).